CTLA4 (cytotoxic T-lymphocyte associated protein 4)
Diseases named in the same sentence as CTLA4 in open-access papers (continued):
Sharing a sentence is not in itself a finding about the gene and the disease.
vitiligo (continued). "As CTLA4 is expressed in Tregs as well as in activated T cells, we suggest that CTLA4 is upregulated in our samples due to increased activation of T cells in the skin of vitiligo patients." (PMID 30515176, 2018). "Adoptive transfers of low numbers of naïve TRP-1-specific T cells into wild-type mice results in overt vitiligo and potent rejection of established B16 melanoma when given in combination with vaccine and IL-2, irradiation and anti-CTLA-4, or in lymphopenic hosts." (PMID 21911918, 2011). "Similarly, following treatment with ipilimumab (anti-CTLA-4), over a third of total responding patients developed autoimmunity, although not limited to vitiligo." (PMID 21911918, 2011). "However, the influence of CTLA4 gene variants in the development of vitiligo has not been analyzed in Mexican patients." (PMID 36163113, 2022). "Thus, this study explores whether the CTLA4 +49 A/G and CT60 A/G gene variants are associated with vitiligo in a Mexican population." (PMID 36163113, 2022). "Two CTLA4 genetic variants have been linked with the development of vitiligo, i.e., +49A/G (rs231775), an exon 1 missense variation leading to a threonine to alanine substitution at codon 17 (T17A); and CT60 A/G (rs3087243), located 236 bp downstream of the CTLA4 3′-UTR." (PMID 36163113, 2022). "However there was significant association of the CTLA-4 genotype (P = 0.02) and allelic frequency (P = 0.008) between the segmental and non-segmental sub groups within vitiligo." (PMID 20418973, 2010). "Highly significant changes in expression of CTLA4 and IL21R were found in growing feathers of vitiligo-expressing Smyth chickens (P < 0.0001)." (PMID 38720888, 2024). "In our study, we found that the weakened immunoregulatory function and proliferative ability of Tregs in vitiligo was accompanied with lower expression of some anti‐inflammatory molecules including TGF‐β, IL‐10 and CTLA‐4." (PMID 29974998, 2018). "As suggested by the analysis of a northeastern Mexican population, the CTLA4 +49A/G (rs231775) and CT60 (rs3087243) gene variants do not constitute a risk factor in the development of vitiligo." (PMID 36163113, 2022). "There was significant difference between the CTLA-4 genotype (P = 0.02) and the allelic frequency (P = 0.008) between segmental and non-segmental vitiligo patients." (PMID 20418973, 2010). "While we hypothesize that expression of CTLA4 is driven by distinct cell populations in Smyth and Brown line chickens, it is possible that a defect in CTLA-4 may be playing a role in permitting and preventing development of vitiligo." (PMID 38720888, 2024). "However, the expression of CTLA4 was increased in vitiligo lesional and non-lesional skin (p < 0.001 and p < 0.001, respectively)." (PMID 30515176, 2018). "Interestingly and besides the appearance of vitiligo-like depigmentation under interferons, no other reports with anti-PD1 or anti-CTLA4 monotherapy have been published so far confirming the prognostic value of irAEs in the adjuvant setting either prospectively or retrospectively." (PMID 34208218, 2021).
triple-negative breast carcinoma (39 papers, 2017 to 2026). An invasive breast carcinoma which is negative for expression of estrogen receptor (ER), progesterone receptor (PR), and human epidermal growth factor receptor 2 (HER2). "CHI3L1, which is generated from triple-negative breast cancer stem cells (TN-BCSCs), causes immunosuppression by improving CTLA4 expression in T cells via MAF and decreasing CD8+ T cell cytotoxicity." (PMID 40097979, 2025). "An OAd armed with GM-CSF was also shown to be greatly enhanced in combination with anti-cytotoxic T lymphocyte-associated antigen-4 (CTLA-4) or anti-PD1 antibodies for the treatment of triple negative breast cancers." (PMID 36851572, 2023). "Currently, the mechanisms underlying the effect of CTLA-4 in triple-negative breast cancer and its interaction with TNBC tumor stem cells remain unclear." (PMID 37838657, 2023). "Similarly, triple combination of vorinostat, anti-PD-1 and anti-cytotoxic T-lymphocyte-associated protein 4 (CTLA-4) agents in triple-negative breast cancer mouse models resulted in significant increases in anti-tumour activity and overall survival compared to monotherapy." (PMID 34439236, 2021). "Taken together, these data suggest that MUC1 mRNA-based vaccination, especially in combination with inhibition of the immune checkpoint CTLA-4, is a promising immunotherapeutic approach for the treatment of triple-negative breast cancer." (PMID 40943370, 2025). "APC, antigen-presenting cells; CTLA-4, cytotoxic T-lymphocyte-associated protein 4; PD-1, programmed cell death protein 1; PD-L1, programmed death-ligand 1; TNBC, triple-negative breast cancer." (PMID 39741315, 2024). "The utilization of CTLA4 blockade remains restricted and the prognosis of cancer can be controlled in specific subtypes of triple-negative breast cancer (TNBC)." (PMID 38397971, 2024). "In the 4T1 triple negative breast cancer model, the effects of anti-PD-1 or anti-CTLA-4 monotherapies were relatively weak." (PMID 35339889, 2022). "In conclusion, we have confirmed an anti-cancer effect of both immunotherapies anti-CTLA-4 and anti-PD-1 in syngeneic tumor models with colorectal and triple negative breast cancer cells." (PMID 35339889, 2022). "Curcumin is a natural product that can reduce tumor cell PDL1 content by promoting its ubiquitination and can improve in vivo anti-CTLA-4 immunotherapy efficacy in murine 4T1 triple-negative breast cancer." (PMID 35563520, 2022). "Dual blockage by combination of anti-CTLA-4 and anti-PD-1 treatments demonstrated better efficiency in the 4T1 triple negative breast cancer model when compared to monotherapy." (PMID 35339889, 2022). "Several clinical trials of PD1/PDL1 blockade, alone or combination with CTLA4 therapy are ongoing in advanced triple negative breast cancer." (PMID 29383101, 2017). "This multicenter, phase II study (NCT03872791) aims to evaluate the efficacy and safety of the anti-PD-L1/CTLA-4 bispecific antibody KN046 combined with nab-paclitaxel in the first-line treatment of patients with metastatic triple-negative breast cancer (TNBC)." (PMID 38310192, 2024). "Thus far, the immune-modifying function of a CTLA4 inhibitor combined with an MUC1 mRNA nanovaccine in the tumor microenvironment (TME) of triple-negative breast cancer (TNBC) has been evaluated by examining the cytotoxic immune cells and cytokines." (PMID 38397971, 2024). "Furthermore, the combination of the Mucin-1 (MUC1)-mRNA DC vaccine with CTLA-4 blockade outperformed either the DC vaccine or CTLA-4 blockade alone in patients with triple-negative breast cancer (TNBC)." (PMID 39062753, 2024). "Here, we investigated whether anti-PD-L1 or anti-CTLA-4 antibodies could modulate the effector functions of NK and T cell subpopulations differently in co-cultures with triple negative breast cancer cells." (PMID 36358708, 2022).
triple-negative breast carcinoma (continued). "However, anti-PD-1/PD-L1 or anti-CTLA4 was mainly used in triple-negative breast cancer (TNBC); thus, we would choose TNBC patients in further studies." (PMID 35686108, 2022). "Nolan and colleagues showed that in BRCA1-mutated triple-negative breast cancers (TNBCs), both mutational loads and the numbers of TIL significantly increased with the accompanying elevation of PD-1 and CTLA4 expression compared to those in the BRCA1-wild type one." (PMID 31023256, 2019). "It has been reported that combined immunotherapy involving the use of anti-CTLA-4 monoclonal antibody and vaccine can modulate the tumor microenvironment and enhance anti-tumor immune response compared to the vaccine or monoclonal antibody alone in triple negative breast cancer." (PMID 35185876, 2022). "In triple-negative breast cancer, immune checkpoint inhibitors may have clinical applications due to “Ras signaling” activation and the elevated expression of immune-related genes such as PD-1, PD-L1, and CTLA-4." (PMID 35317849, 2022). "This fits with the results of a previous gene-expression study, in which we were able to show that a CPS consisting of CTLA-4 and PD-1 had a significant impact in terms of MFS in a subset of triple-negative breast cancers." (PMID 36289918, 2022). "Anti-PD-1 and anti-CTLA-4 alone or in combination displayed different anti-cancer efficacy between the CT26 colorectal and the 4T1 triple negative breast cancer models." (PMID 35339889, 2022). "In this study, anti-tumor CTL activity induced by combination of CTLA-4 Blockade with MUC1 mRNA nanovaccine and immunosuppressive factors in the TME of triple negative breast cancer were investigated." (PMID 34875483, 2022). "For CoCNV, some genes in the PMI network gene set can classify patients into groups with significantly different survival probability by their single gene CNV, such as CTLA4, ORM1, and RASAL3 in triple negative breast cancer." (PMID 35610556, 2022). "Moreover, in advanced triple-negative breast cancer (TNBC), patients exhibiting higher plasma levels of TIM-3 or CTLA-4 have shown better responses to anti-PD-1 immunotherapy combined with VEGFR-2 targeted treatments." (PMID 40724985, 2025). "We tested the impact of EHMT2 knockdown in triple-negative breast cancer (TNBC) cells, a cancer type that is not very responsive to adaptive immune checkpoint blockade therapies (anti-PD-1, anti-CTLA4, etc.)." (PMID 41366520, 2026).
atherosclerosis (38 papers, 2013 to 2026). A disease characterized by the build-up of fatty material and calcium deposition in the arterial wall resulting in partial or complete occlusion of the arterial lumen. "Although the role of CTLA-4 and PD-1 in regulating the inflammatory response underlying atherosclerosis is established, the effects of ICIs on atherosclerosis in cancer patients are not completely understood." (PMID 39621799, 2024). "Lastly, ICI therapy-associated atherosclerosis has provided additional insights into the potential risk factors for anti-PD-L1 therapy or combined anti-PD-L1 and anti-CTLA4 therapy." (PMID 38136253, 2023). "Several animal and cell experiments have demonstrated that programmed cell death protein 1 (PD-1), programmed death ligand 1 (PDL-1), and cytotoxic T-lymphocyte-associated protein 4 (CTLA-4) are key negative regulators of atherosclerosis." (PMID 36742069, 2023). "The protective role of CTLA-4 against atherosclerosis has been investigated in a study on transgenic apolipoprotein E-deficient (Apoe−/−) mice with constitutive cell surface and intracellular expression of CTLA-4 in T cells." (PMID 41009661, 2025). "Interestingly, while cancer and atherosclerosis share similarities in their inflammatory-dependent pathophysiology, ICI mAbs, specifically CTLA-4 and PD-1–PD-L1 blocking antibodies, have been shown to increase cardiovascular events associated with atherosclerosis." (PMID 40552286, 2025). "We also identify key regulatory axes, such as CD47/Sirpa and Selplg/Vsir in AAA, and CD48/CD2, CD86/CD80, and CTLA-4/PD-1 in atherosclerosis, as potential therapeutic targets." (PMID 41216502, 2026). "In hypercholesterolemic ApoE3*Leiden mice, co-stimulation blockade with the CTLA-4 fusion protein abatacept attenuated atherosclerosis development via reducing T-cell activation, decreasing circulating IFNγ and increasing IL-10 levels." (PMID 39023770, 2025). "Mice overexpressing CTLA-4 have defective effector T cell responses and developed less atherosclerosis." (PMID 39817455, 2025). "CTLA-4 immune checkpoints have been found to facilitate the thymocyte-mediated inflammatory development of atherosclerosis." (PMID 40255399, 2025). "Pharmacological inhibition of CD28-CD80/CD86 with the CTLA-4–Ig fusion protein abatacept reduced atherosclerosis in mice." (PMID 39817455, 2025). "In mouse models, T lymphocytes correlate with the development of accelerated atherosclerosis, and the co-stimulation of CD28-CD80/86 T cells and CTLA4-mediated inhibition also appear to correlate with the severity of atherosclerosis in RA." (PMID 38929699, 2024). "In summary, experimental models of atherosclerosis have provided insights into the role of the PD-1/PD-L1 dyad and CTLA-4 in suppressing T-cell-driven inflammation, thereby limiting plaque development, progression, and instability." (PMID 38473748, 2024). "Treatment with soluble agonist CTLA-4 Ig fusion protein reduced atherosclerosis progression in hyperlipidemic and hyperhomocysteinemic ApoE−/− mice by competitively inhibiting CD28-CD80/86 co-stimulatory T-cell activation and pro-inflammatory cytokine release." (PMID 39926714, 2024). "Conversely, inhibiting CTLA-4 using antibodies or the dual inhibition of CTLA-4 and PD-1 accelerates atherosclerosis with increased T-cell-driven endothelial inflammation and plaque area." (PMID 38473748, 2024). "Blockading CTLA-4 increases T cells abundance in plaques and exacerbates atherosclerosis in mouse model." (PMID 36911712, 2023). "Treatment with anti-PD-1 and anti-CTLA-4 antibodies reduced tumor burden but increased pro-inflammatory T-cell activation, leading to atherosclerosis progression." (PMID 37297017, 2023). "Overexpression of CTLA-4 prevented the development of atherosclerosis by suppressing the activation of effector CD4+ T cells and restricting their accumulation along the arterial wall in hyperlipidemic mice." (PMID 37297017, 2023).
atherosclerosis (continued). "Another study demonstrated that CTLA-4 overexpression dramatically decreased the development of atherosclerosis and the intraplaque concentration of macrophage and CD4 (+) T cells in the aortic root as compared with controls." (PMID 36703734, 2022). "Studies have shown that single programmed cell death protein 1(PD-1), T cell immunoglobulin and mucin domain 3 (Tim-3), or cytotoxic T-lymphocyte antigen-4 (CTLA-4) pathway signaling has anti-atherogenic effects during the progress of murine atherosclerosis." (PMID 35757718, 2022). "The immunological checkpoint proteins CD80/86-CD28/CTLA4 are essential regulators of atherosclerosis that either promote or suppress plaque inflammation." (PMID 36703734, 2022). "Previous studies have revealed that single PD-1, Tim-3, or CTLA-4 pathway signaling has anti-atherogenic effects during the progress of murine atherosclerosis." (PMID 35757718, 2022). "Our recent study demonstrated that overexpression of CTLA-4 in T cells inhibited atherosclerosis development in Apoe−/− mice by downregulating the CD80 and CD86 expression on DCs and limiting the CD80/CD86–CD28-dependent activation of Teffs." (PMID 34945203, 2021). "Together, these studies and our findings identify a protective role for CTLA4 in atherosclerosis, where it potentially decreases lymphoid-driven inflammation, and thereby limits macrophage death and plaque progression." (PMID 32872393, 2020). "Our observations are in line with previous studies that explored the role of the CD80/86-CD28 and -CTLA4 pathways in atherosclerosis." (PMID 32872393, 2020). "For example, the T cell-specific overexpression of CTLA4 reduced atherosclerosis in ApoE−/− mice and limited the numbers of CD4+ T cells and macrophages in the plaque and decreased systemic T cell activation." (PMID 32872393, 2020). "Under hyperlipidemic conditions, T cell specific overexpression of CTLA-4 limits T cell activation and hampers their accumulation in the arterial wall, thereby ameliorating atherosclerosis." (PMID 34396271, 2020). "Here, we report that the short-term antibody-mediated inhibition of CTLA4 aggravates experimental atherosclerosis by accelerating the progression of initial plaques towards more advanced and unstable lesions." (PMID 32872393, 2020). "The short-term antibody-mediated inhibition of CTLA4 thus accelerated the progression of atherosclerosis by inducing a predominantly T cell-driven inflammation, and resulted in the formation of plaques with larger necrotic cores and less collagen." (PMID 32872393, 2020). "Our recent work using atherosclerosis-prone CTLA-4 transgenic (CTLA-4-Tg) mice demonstrated a protective role of this inhibitory molecule in the development of experimental atherosclerosis." (PMID 31147569, 2019). "The administration of the CTLA4-Ig fusion protein to hypercholesterolemic mice substantially reduces atherosclerosis, whereas a CTLA4 blockade accelerates disease." (PMID 29867939, 2018). "Moreover, ICIs, involving anti-PD-1, anti-CTLA-4, anti OX40, and others, have been associated with immune-mediated myocarditis, pericarditis, and accelerated atherosclerosis." (PMID 40227756, 2025). "Summary of mouse models of atherosclerosis induced by PD-1 and CTLA-4 pathway inhibition." (PMID 40821806, 2025). "This indicates that CTLA-4 inhibition, like PD-1 inhibition, induces an activated phenotype of T cells, and the inhibition of different immune checkpoint pathways has differential effects on the activation of immune cell components in atherosclerosis." (PMID 40821806, 2025).